KRT19 (keratin 19)
Diseases named in the same sentence as KRT19 in open-access papers (continued):
Sharing a sentence is not in itself a finding about the gene and the disease.
tumor (continued). "We found that folate receptor 1 (FOLR1), a known secretory protein, was upregulated in tumor tissues and positively associated with 3 major stem/progenitor markers, KRT19, EPCAM, and PROM1, and a poor prognosis for HCC patients in both the discovery and validation cohorts." (PMID 40038575, 2025). "Furthermore, others have found that the presence of fibrous tumor stroma is associated with keratin 19 expression for HCCs, which is a poor prognostic marker for this disease." (PMID 38047594, 2023). "Furthermore, the increase in NLR has been associated with tumor expression of cytokeratin 19 (CK19), and consequently a more aggressive tumor behavior with weaker prognosis." (PMID 36230569, 2022). "Here, we proposed that further identification and functional elucidation of KRT19 associated LncRNAs could provide new insights into KRT19-mediated tumor promotion in HCC." (PMID 33767587, 2021). "In addition, KRT19, which is responsible for maintaining the structural integrity of epithelial cells, was reported as tumor-associated proteins as its down-expression was identified in ESCC in a proteomic study." (PMID 34795689, 2021). "In addition, a high MoRAL score was associated with cytokeratin 19 expression, which is a stemness-related marker and reflects tumor invasiveness, among patients who underwent surgical resection for HCC." (PMID 31689972, 2019). "Using univariate and multivariate analysis, cytokeratin-19 and glypican-3 expression patterns, tumor number and histological grading from eight putative prognostic factors comprised the risk factor scoring model to predict the tumor recurrence." (PMID 28968990, 2017). "In addition to cytomorphological analysis, gene expression of tumor associated genes (Cytokeratin-18, Cytokeratin-19, Cytokeratin-20, Cytokeratin-7, EPCAM, MUC1, HER2, EGFR) and of leukocyte markers (e.g. CD45, CD68) was tested in enriched CTC fractions." (PMID 25862542, 2016). "Based on the clinical information analysis, we found that the miR-26a and KRT19 was highly associated with the tumor size of patients, indicating that miR-26a might act an important role in the tumorigenesis of CCA." (PMID 27833076, 2016). "Furthermore, precise cut-off levels between mRNA amounts of normal blood cells and tumor cells must be determined and validated since tumor-associated targets such as KRT-19 mRNA have also been found in a small number of healthy individuals." (PMID 25398926, 2015). "Downregulation of KRT19 gene expression was highly associated with tumor progression in NB." (PMID 23135478, 2013). "Notably, the hypoxia/glycolysis signature contains intestinal differentiation markers (e.g., TFF3, FABP1, KRT19), indicating an association of distinct metabolic states with tumor cell differentiation and proliferation, as recently described for the normal intestinal crypt." (PMID 33806447, 2021). "Cytokeratin 19 (CK19) is an important immunohistochemical marker reflecting tumor invasiveness and metastatic potential; however, noninvasive preoperative prediction of CK19 expression remains unavailable." (PMID 42224263, 2026). "PPC tumor epithelial cells were positive for CK19 (cytokeratin 19), phospho-extracellular signal regulated kinase (ERK), and Ki67, similar to those of PKC mice." (PMID 40638603, 2025). "In the CD45− population, clusters 0 and 1 were identified as major tumor clusters exhibiting high expression levels of epithelial cell markers (Krt8, Krt18, Krt19)." (PMID 40568084, 2025). "Clusters 20 and 12 from the original UMAP (Figure A4b) were identified as PDAC tumor cells based on their expression of marker genes, including Sox9, Krt7, Krt19, or Epcam." (PMID 39857986, 2025). "In the OSNA system, the number of cytokeratin 19 mRNA copies per μL of the tumor sample is determined." (PMID 39859370, 2025). "KRT19 interacts with long non-coding RNAs to activate signaling pathways related to tumor proliferation and metastasis." (PMID 41153430, 2025).
tumor (continued). "Then, we investigated the effect of Krt19 inhibition and anti-PD-1 immunotherapy on tumor-infiltrating CTLs." (PMID 41345704, 2025). "We used keratin expression (KRT7, KRT8, and KRT19) to visualize the tumor area and CD68 to mark myeloid cells." (PMID 40917508, 2025). "Compared with the EV group, mice received KRT19-overexpressing A549 cells showed increased tumor growth rate and tumor weight, which also exhibited higher Ki-67 levels in tumor tissues determined by immunohistochemical staining." (PMID 41345704, 2025). "Next, we compared their expression with the GTEx database, except KRT19, as it is a well-known marker of PDAC, strongly associated with tumor progression and diagnosis." (PMID 40507294, 2025). "WA treatment significantly reduced tumor burden and decreased cytokeratin 19-positive (CK19+) malignant cells, alongside diminished lipid droplet accumulation." (PMID 41291880, 2025). "Subsequent tumor cell breakdown releases cytokeratin 19 fragments, thereby elevating serum CYFRA 21-1 levels." (PMID 41007708, 2025). "XCELL analysis further identified a negative correlation between intratumoral CTLs infiltration level and tumor KRT19 expression in NSCLC." (PMID 41345704, 2025). "More significantly, blockade of KRT19 potently enhanced the cytotoxic function of tumor-infiltrating CD8+ T cells and synergistically repressed NSCLC progression when combining with anti-PD-1." (PMID 41345704, 2025). "Regarding serum tumor markers, cytokeratin-19 fragment (CYFRA 21-1) and carcinoembryonic antigen have been proven to be prognostic indicators for NSCLC patients." (PMID 41377338, 2025). "The total tumor load (TTL) was defined as the sum of cytokeratin 19 mRNA copies/μL in all LNs from a surgical specimen, using a threshold of 250 copies/μL for OSNA positivity." (PMID 40647439, 2025). "We focused on 3 stem/progenitor markers, KRT19, EPCAM, and PROM, which are known to be associated with tumor aggressiveness." (PMID 40038575, 2025). "The one-step nucleic acid amplification (OSNA) test semi-quantitatively detects the number of cytokeratin 19 mRNA copies, a well-known tumor marker, which can be used to infer the presence of metastases in non-sentinel lymph nodes (SLN)." (PMID 39859370, 2025). "Both SCC and cytokeratin 19 fragment showed progressive elevation during serial tumor marker monitoring." (PMID 41040533, 2025). "In this study, we assessed the impact of KRT19 on NSCLC using xenograft tumor models, EdU, CCK8, colony formation and transwell assay." (PMID 41345704, 2025). "Inducing Prox1 OE after 21 days of HDTVI-mediated tumor formation also decreased glandular structures and reduced cholangiocyte marker expression (KRT19 and SOX9)." (PMID 39948437, 2025). "KPC tumors displayed reduced epithelial cytokeratin-19 protein expression and reduced tumor growth in all Tert KO models." (PMID 40482194, 2025). "Comprehensive and integrated unraveling the intricate crosstalk and the dynamic molecular regulatory network of KRT19/MYH9 complex in dictating cell properties among different tumor types is of interest and needs further investigation." (PMID 41345704, 2025). "In summary, these data verified that KRT19 knockdown enhances anti-PD-1 immunotherapy efficiency by potentiating stronger anti-tumor responses of tumor-infiltrating CTLs." (PMID 41345704, 2025). "Inspiringly, intervention of KRT19 in NSCLC cells enhanced anti-PD-1 immunotherapy efficiency by potentiating stronger antineoplastic responses of tumor-infiltrating cytotoxic CD8+ T cells (CTLs)." (PMID 41345704, 2025). "Strikingly, Prox1 knockdown induced a shift from HCC toward CCA, forming glandular tumor structures expressing KRT19 and decreased HNF4 levels." (PMID 39948437, 2025).
tumor (continued). "Immunofluorescence staining revealed that NAT10 staining was strongly positive in a large fraction of cytokeratin 19 (CK19) + tumor cells." (PMID 40119353, 2025). "The levels of tumor markers, such as carcinoembryonic antigen and cytokeratin-19-fragment, were reduced in fifteen patients." (PMID 38414743, 2024). "In contrast, downregulation of KRT19 has been reported in tumor breast tissue compared to adjacent tissue, and it has been associated with an aggressive phenotype and chemoresistance of cancer cells." (PMID 38510654, 2024). "Fortunately, the patient experienced substantial pain relief, and tumor markers decreased significantly from pre-treatment levels (cytokeratin 19 fragment and neuron-specific enolase levels dropped to 24.90 ng/ml and 23.20 ng/ml, respectively)." (PMID 38979408, 2024). "At the time of necroscopy, the tumor marker Krt19 was used to verify comparable levels of tumor burden among the collected pancreata samples." (PMID 38342897, 2024). "Serum levels of cytokeratin 19 fragment (71.50 ng/ml) and neuron-specific enolase (139.00 ng/ml) were elevated, while the levels of other tumor markers were within the normal range." (PMID 38979408, 2024). "Cell clusters obtained were characterized based on their gene expression profile and identified as B16F10 tumor cells (Pmel, Mlana), mT4 tumor cells (Krt18, Krt19), and fibroblasts (Col1a1, Dcn)." (PMID 38987547, 2024). "In favour of phagocytosis of tumour cells, KCs contained abundant tumour-derived material in short-term and long-term orthotopic models and the endogenous KPC tumour model with spontaneous metastases, as visualized by tdTomato (tdT) or KRT19 staining." (PMID 38326607, 2024). "In HNSCC and OSCC in other types of KRT (KRT17, KRT19), similarly to ours, increased protein levels were observed in the tumor compared to the healthy sample or surgical margin." (PMID 39000463, 2024). "To depict the characteristics of ICC spatial organization in the leading‐edge (L) area, we used ALB and KRT19 to define the tumor side and non‐tumor side on the L‐area slice (left)." (PMID 39716897, 2024). "Serum tumor marker assessment indicated elevated levels of neuron-specific enolase at 27.22 ng/mL and cytokeratin 19 fragment (Cyfra 21–1) at 3.43 ng/mL, whereas other tumor markers were within the normal ranges." (PMID 38903719, 2024). "Consistent with gene expression data, staining with Krt19 highlighted a subset of tumor cells with variable expression of Krt19." (PMID 39051113, 2024). "The specificity of this analysis was supported by the downregulation of the acinar and insular cell markers AMY2B and INS, while the expression of the tumor marker KRT19 was increased (Fig. EV3A)." (PMID 38413734, 2024). "Both hepatocyte markers (eg, HepPar1, arginase-1, and α-fetoprotein) and cholangiocyte markers (eg, cytokeratin 19 and carcinoembryonic antigen) are expressed in the tumor cells of int-CA." (PMID 39101773, 2024). "Histochemical analysis revealed positive staining for both A/N+shEzh2#1, A/N+shEzh2#2 and A/N+C transfection‐induced tumour cytokeratin 19, a classical biomarker for CCA and the knockdown effects of Ezh2 were also demonstrated by histochemical staining." (PMID 38050190, 2023). "All tumor cells showed high expression in signature genes of pancreatic epithelial lesion, like KRT19, MUC1, EPCAM and CEACAM6." (PMID 37007745, 2023). "Univariate analysis determined tumor recurrence using cytokeratin 19 fragment, CA-199, CEA, N-stage, positive lymph nodes, total lymph nodes, and lymph node ratio(positive/total); with the lymph node ratio being the most relevant." (PMID 38023220, 2023). "These DCs contained several specific tumor-associated antigenic determinant genes, including carcinoembryonic antigen (CEA), cytokeratin 19 (CK19), and prostate specific membrane antigen (PSMA), highlighting the potential of ACT therapies in treating BrM." (PMID 37056723, 2023).
tumor (continued). "The expression of CD14 (monocyte and macrophage marker) showed opposite trends from the expression of KRT19 (malignant cells marker), suggesting that monocytes or macrophages were enriched in normal regions compared with tumour regions." (PMID 37401015, 2023). "Other clinicopathological or molecular markers have recently been considered promising predictors of prognosis in colorectal cancer, such as serum CEA, serum CA-199, serum cytokeratin 19 fragment, and degree of tumor differentiation." (PMID 38023220, 2023). "Histological analysis showed positive staining for cytokeratin 19 in both A/N+E2 and A/N+V transfected induced tumours, and histochemical staining further demonstrated the overexpression effects of Ezh2." (PMID 38050190, 2023). "Histological analysis showed positive staining for cytokeratin 19 in both A/N+Sfrp1 and A/N+V transfected induced tumours, and histochemical staining further demonstrated the overexpression effects of Sfrp1." (PMID 38050190, 2023). "Cytokeratin 19 (CK19), with a molecular weight of 40kDa, is the least acidic type I cytokeratins (CKs) which has been considered a tumor prognostic and metastatic marker in varied cancers." (PMID 37519791, 2023). "KRT19 (tumor epithelial cells), PTPRC (CD45; immune/hematopoietic cells), and PDGFRB (stromal cells) were highly expressed by cells in different clusters." (PMID 37966117, 2023). "Previously, it was mentioned that an increase in hepatic stem cell protein expression of cytokeratin 19, CD133, and CD44 is closely associated with tumor angiogenesis and poor prognosis." (PMID 37835585, 2023). "Cyfra21-1 is a fragment of cytokeratin-19, which is present in the cytoplasm of monolayer and stratified epithelial tumor cells." (PMID 36246602, 2022). "Consistently, some previously reported genes associated with tumor progression, such as APOH and KRT19, were also gradually upregulated with the development of pseudo-time trajectories." (PMID 36386204, 2022). "Phagocytosis was evaluated using dual immunofluorescence analysis of tumor cell marker cytokeratin 19 (CK19) and macrophage marker F4/80." (PMID 36333531, 2022). "In this regard, a study evaluated the relationship between the CTC-positive status of patients with mRCC and the expression of blood tumor markers, namely cytokeratin 19 (CK19), endoglin (CD105) and CD146." (PMID 36612281, 2022). "CYFRA21-1, a fragment of cytokeratin 19, is mainly expressed in tumor cells of epithelial origin and can be used as a marker for epithelial cancers." (PMID 36326305, 2022). "Clustered stromal cells corresponded to endothelial cells (positive for PECAM1/CD31, VWF), normal fibroblasts (FN1, EGFL6), tumor-associated fibroblasts (TAFs; PDGFRA, ADH1B), and thymic epithelial cells (TECs; KRT19, S100A14)." (PMID 35869073, 2022). "Autofluorescence of the tissue (imaged at 488 nm of excitation) provided sufficient structural information to accurately identify the contours of the tumor, as confirmed by immunostaining for cytokeratin 19 (CK19)." (PMID 35418199, 2022). "Some well-known marker genes were used to identify cell types, such as EPCAM and KRT19 for tumor cell, COL1A1 and ACTA2 for CAF, CD3D and CD3E for T cell, and CD68 and CD14 for macrophage." (PMID 36499343, 2022). "The presence on the cell surface of CXCL12 and KRT19 was confirmed by flow cytometric analysis of single-cell suspensions of intact tumor cells." (PMID 35046049, 2022).
tumor (continued). "The proteolytic region of cytokeratin-19, referred to as Cyfra 21-1, is a soluble molecule present in the serum and other body fluids and is considered a tumor marker in several neoplastic diseases." (PMID 35330146, 2022). "We found that metastatic tumour cells (cytokeratin 19+) in both chemotherapy-treated patient cohorts were surrounded by higher numbers of neutrophils (MPO+) compared with the untreated patient cohort." (PMID 35022267, 2022). "Consistent with PTC features in humans, we observed increased levels of cytokeratin 19 (KRT19, hereafter referred to as CK19) in tumor cells of mutant mice." (PMID 34379110, 2022). "Soluble protein fragments of keratins, including KRT7, KRT8, KRT18 and KRT19, can be detected in the circulation of cancer patients and are used to monitor disease progression and patient prognostic in certain tumour types." (PMID 34070214, 2021). "A novel molecular technique for the detection of LN metastases of tumors, called one‐step nucleic acid amplification (OSNA), is a rapid and semi‐quantitative examination quantifying the number of cytokeratin 19 (CK‐19) mRNA copies derived from a tumor." (PMID 33532681, 2021). "H&E and cytokeratin 19 staining of lung and liver tissues were performed to assess tumor cell metastasis." (PMID 33937232, 2021). "In accordance with previous conclusion, the relative abundance of KRT19 mRNA increased 2- to 3-fold when normal tissue transformed into tumor (t-test, p<0.001)." (PMID 33442422, 2021). "KRT19 (Cytokeratin 19), one of the smallest members of the acidic type I cytokeratin family proteins (KRTs), has been reported as widely detectable tumor maker in various cancers, including HCC 4-7." (PMID 33767587, 2021). "KRT19 has been demonstrated as a tumor promoting factor in various tumors, including HCC, whereas the detailed underlying mechanisms are still sciolistic 5-7." (PMID 33767587, 2021). "The total tumor load, defined as the amount of cytokeratin 19 mRNA copy numbers in all positives SLN (copies/μL), showed three risk groups related to the possibility of positive non-sentinel nodes." (PMID 33435629, 2021). "Immunohistochemistry showed that the tumor was positive for cytokeratin 19 (CK19), S-100, vimentin, mammagloblin, gross cystic disease fluid protein 15 (GCDFP15), and GATA3." (PMID 34941172, 2021). "Three epithelial cell clusters (Epi_KRT19, Epi_STMN1, Epi_FABP1) were almost only presented in tumor tissues." (PMID 35087839, 2021). "Cytokeratin 19 (CK19) is well acknowledged as a biliary/progenitor cell marker and a marker of tumor stem cell." (PMID 32742454, 2020). "Recently, it was shown that the circulating levels of cytokeratin 19 fragment (CYFRA 21-1) are able to reflect tumor K19 expression." (PMID 32998218, 2020). "Immunohistochemical analysis and immunofluorescence staining for cytokeratin 19, proliferating cell nuclear antigen, and α-smooth muscle actin were performed in tumor and peritumor liver tissues." (PMID 33008300, 2020). "The OSNA (One-Step Nucleic Acid Amplification) assay provides a quantitative value of the metastatic burden of the sentinel lymph node (SLN) by measuring the mRNA expression of the tumour marker cytokeratin 19 (CK19)." (PMID 33008422, 2020). "These sequential invasion events mimic what happens in our in vivo model, whereby fibroblasts (α‐SMA‐positive cells) precede tumour cells (cytokeratin 19‐positive cells) during the invasion process into the spleen (Fig EV4D)." (PMID 33025708, 2020). "Tumors in vehicle treated mice showed a less differentiated architecture, with a higher percentage of stromal cells and fewer tumor cells (cytokeratin 19 positive cells)." (PMID 33396954, 2020). "In other gastrointestinal cancers, clinical-pathological analyses revel KRT19 correlated with metastasis, tumor size, microvascular invasion, decreased tumor differentiation, and also conferred an invasive phenotype." (PMID 32005189, 2020).